KIT (KIT proto-oncogene, receptor tyrosine kinase)
Diseases named in the same sentence as KIT in open-access papers (continued):
Sharing a sentence is not in itself a finding about the gene and the disease.
tumor (continued). "In addition, activation of KIT promotes ovarian CSC survival and self-renewal, indicating that KIT regulates not only normal stem cells but also CSCs of certain tumour types." (PMID 34718356, 2022). "In addition to its role in regulating cell proliferation, c-KIT appears to be involved in regulating the survival and activation of mast cells, cells involved in tumor-microenvironment interaction in the canine PC." (PMID 35681707, 2022). "Additionally, it has been reported that gastrointestinal stromal tumour (GIST) cells release EVs that similarly contain oncogenic KIT with tumour‐promoting activities and that KIT‐containing exosomes can be isolated from GIST cell lines and patient plasma." (PMID 36239715, 2022). "The objective was to assess the frequency of KIT gene alterations, and other relevant somatic and germline genetic variants, in a Polish cohort of TET patients, and to correlate the genetic findings with the pathological and clinical features of these tumours." (PMID 35884448, 2022). "The increased tumor angiogenesis in this model is related to enhanced endothelial Vegf receptor 1, 2, and 3; platelet-derived growth factor receptor beta (Pdgfrβ); platelet-derived growth factor subunit B (Pdgfb); and tyrosinkinase KIT (c-kit) expression." (PMID 35954274, 2022). "Thirteen of the 21 tumours demonstrated a degree of positive staining for Cox-2 and four for c-KIT." (PMID 36290122, 2022). "In addition, the KIT mutation co-occurred with CCND1 amplification in 0.33% (1/302), 0.82% (3/367), and 0.57% (2/350) of tumor samples in the Geneplus, TCGA, and MSKCC cohorts, respectively." (PMID 35844619, 2022). "Moreover, KIT has been implicated in EC migration, proliferation and tube formation through in vitro studies, and decreased KIT expression reduces angiogenesis in mouse models of ocular pathology and tumours." (PMID 35416527, 2022). "Conversely, for NCCS-GIST-09, despite disease progression, no KIT variant, as previously detected in tumor, was detected in ctDNA collected at the different time points." (PMID 35273917, 2022). "Striking differences were observed between normal and tumor cells for proto-oncogene KIT." (PMID 35884847, 2022). "Interestingly, KIT also provides protection against tumor-suppressive TGFβ signaling, possibly by reducing the expression of SMAD2." (PMID 35842424, 2022). "Indeed, different studies in mice have demonstrated that high levels of c-KIT on mast cells and their presence in the tumor microenvironment promote angiogenesis, leading to increased tumor growth and metastasis." (PMID 35490363, 2022). "The role of c-KIT in tumors is highlighted by the reports that treatment with its inhibitors, the Imatinib Mesylate (Glivec) and Sunitinib (Sutent) (targeted cancer therapy), result in the inhibition of the tumor cells of some cancers." (PMID 34439864, 2021). "Overall, neither relative nor absolute abundance of tumor microenvironment subpopulations allowed to clusterize SDH-deficient GISTs separately from KIT-mutant GISTs; however, the t-test analysis at single subpopulation level depicted some noteworthy evidences." (PMID 33806389, 2021). "A clinical study using IM in combination with the CTLA-4 inhibitor Ipilimumab in 10 patients with advanced GISTs showed that 9 patients (8 with mutations in KIT exon 11 and 1 with a mutation in KIT exon 13) all progressed, but in 1 case of WT GIST, the tumor shrank by 68%." (PMID 34956906, 2021). "Deletions affecting codons 557–558 of exon 11 of the KIT gene have been reported in up to 28% of all GISTs and have been associated with high-risk tumors, having higher mitotic index (>5/50 HPF) and larger (>5 cm) tumor size." (PMID 33525726, 2021). "Factors such as primary tumor size or location, mitotic activity, as well as rupture of the tumor either prior to or during surgery, failure to obtain clear margins during surgery, and deletions in KIT exon 11 are known to contribute to the malignant potential of GISTs." (PMID 34442339, 2021).
tumor (continued). "Wild-type GIST (wtGIST) refers to tumours that are negative for KIT and PDGFRA gene mutations and account for 15% of adult and 85% of paediatric GIST." (PMID 33443647, 2021). "After treatment with the antibody, tumor cells showed a decrease in KIT expression, leading the authors to consider that the mechanism by which the antibodies affect the cells is a downregulation of KIT, and through augmenting phagocytosis of GIST cells by macrophages." (PMID 34298737, 2021). "Out of five patients, 40% had somatic tumor mutations present in KDR and/or KIT in ccfDNA." (PMID 34298235, 2021). "Disruption of the TGF-β/KIT signaling loop on the level of the SCF/STAT3 axis restores TGF-β tumor suppressor function by inhibition of epithelial-mesenchymal transition (EMT), tumor cell migration, and invasion, and restoration of its cell cycle inhibitory functions." (PMID 33603771, 2021). "Also, in EGIST, the degree of KIT and PDGFRA mutations varies on where the location of the tumor is." (PMID 32703220, 2020). "Furthermore, YA patients significantly more often had non-KIT/PDGFRA positive tumours than patients in the OA group (25% vs. 11%, respectively; p = 0.008)." (PMID 32244864, 2020). "The 729 diagnostic tumor samples that were evaluated with the smMIP panel showed 788 (likely) pathogenic mutations, including mutations that give access to targeted treatment options (e.g. mutations in EGFR, BRAF, MET, ERBB2, KIT, PDGFRA)." (PMID 32264863, 2020). "In addition to KIT variations, somatic mutations in other genes also occur in ASM that facilitate tumor growth." (PMID 33246418, 2020). "For KIT and PDGF-a molecular mutations, analysis is strongly encouraged to be performed in cases with failure to imatinib mesylate therapy response, incomplete tumor resection, or metastasis especially for patients diagnosed with a high-risk group pathology." (PMID 33042684, 2020). "ctDNA evaluation might impact particularly in tumor types associated with recurrent driver genetic events, such as GIST, a rare neoplasm of mesenchymal origin whose course of disease is governed by KIT or PDGFRA oncogenic activation." (PMID 32024476, 2020). "Interestingly, GIST_260 and GIST_307 additionally showed a combined membranous, cytoplasmic, and paranuclear Golgi-like positivity, suggestive of a diffuse alteration of KIT expression in the tumor mass." (PMID 32391261, 2020). "Abnormal expression of KIT has been documented in various neoplasms." (PMID 32984034, 2020). "Protooncogene c-KIT/CD117 is known as the mast/stem cell factor receptor and receptor tyrosine kinase, and its activation in CSCs may regulate the stemness to control tumor progression and drug resistance to tyrosine kinase inhibitors." (PMID 32855630, 2020). "Interestingly, inhibition of c-KIT with imatinib in combination with cisplatin/paclitaxel suppressed tumor growth in OC cells and in vivo models." (PMID 32512891, 2020). "We did not identify substantial heterogeneity of KIT secondary mutations neither in plasma nor in tumor tissue, which agrees with previous PCR-based studies and more recent plasma NGS reports." (PMID 32024476, 2020). "Then, to determine the indication of adjuvant therapy, we performed a genetic examination of the tumor, which revealed no KIT mutation but instead revealed a PDGFRA D842V substitution." (PMID 32703220, 2020). "Indeed, given its key role, the gene coding for the KIT protein (KIT) received great attention in the field of human oncology, particularly in the study of neoplasms of melanocytic origin." (PMID 33321993, 2020). "To date, the IHC evaluation of KIT expression has been limited to a semi-quantitative evaluation, expressed as classes corresponding to an approximate percentage of immunoreactive cells on the total tumor area, often with wide ranges defining a single class." (PMID 33321993, 2020). "In addition, c-KIT not only functions on ECs but also belongs to the tumor angiogenesis-promoting molecule." (PMID 32855630, 2020).
tumor (continued). "RTKs, such as VEGF receptor, EGFR, fibroblast growth factor receptor, platelet-derived growth factor receptor, RET and KIT, are responsible for several biological signaling pathways involved in the regulation of angiogenesis, oncogenesis and the tumor microenvironment." (PMID 31856912, 2019). "Moreover, the immunoexpression levels of the total KIT were lower in tumor tissues obtained from the groups treated with high-dose VPA or IM combined with low-dose VPA than in the control group." (PMID 31363162, 2019). "However, in cases with a risk of recurrence and cases of progressive GIST, KIT and PDGFRA genotyping is important for the assessment of drug sensitivity and tumor aggressiveness." (PMID 31410732, 2019). "PDGFRα and KIT, targets of the multi-kinase inhibitor sunitinib which is one of the current choices of first-line drug in metastasized ccRCC patients, were expressed at relatively low levels in tumor tissues, whereas significantly increased in normal kidney." (PMID 30881919, 2019). "Notably the 3.2N population had a region of increased copy number gain internal to the region of overlap that included KIT suggesting ongoing selection during the clinical history of the tumor." (PMID 30870501, 2019). "KIT is a proto-oncogene and its overexpression may have detrimental consequences such as tumor development." (PMID 31841508, 2019). "As the majority of resistance mechanisms to BRAFi + MEKi are related to the MAPK pathway, we may assume that this baseline tumor-suppressor effect of KIT is emphasized in our cohort, improving the clinical course under BRAFi + MEKi." (PMID 31426590, 2019). "Primary AML tumor samples were selected based on having known HLA haplotypes for HLA-A, B, C and HLA-DR, and at least one or more common recurrent mutations in either NPM1, FLT3, DNMT3A, IDH1, IDH2, KIT, or RAS from previous clinical evaluation." (PMID 31291378, 2019). "Moreover, inhibition of SCF-c-KIT signaling prevented enrichment of CSC cells as well as diminished tumor-initiating capacity of the RH1 resistant cells." (PMID 31336714, 2019). "Plasma from one patient (patient 6) with metastasized disease had no detectable mutant ctDNA while a KIT mutation was detected in the pre-treatment tumor biopsy." (PMID 29568401, 2018). "Finally, a connection was found between c-KIT gene mutations, elevated c-KIT mRNA expression and a higher grade of tumor." (PMID 29915788, 2018). "The tumour showed high expression of KIT in the high grade component of the tumour." (PMID 29357824, 2018). "Yet, in KNGL cases, the role of KIT in tumour pathogenesis may be limited, which indicates that the prognostic value of the miRNAs may also be by targeting other genes, besides KIT." (PMID 29707131, 2018). "Radio- and cytostatic chemotherapy are less effective against tumor cells that divide slowly, and the absence of c-KIT mutations makes the tumors less likely to respond to protein kinase inhibitors." (PMID 29915788, 2018). "Gain-of-function mutations in the growth factor receptor genes for KIT (CD117) and platelet-derived growth factor α (PDGFRA) drive tumor development in 85–90% of GISTs to promote constitutive activation of growth factor signaling pathways that cause uncontrolled cell proliferation." (PMID 30450193, 2018). "Available archival FFPE tumor tissue from 27 consecutive patients with known KIT exon 11 mutations and 9 randomly selected patients without exon 11 mutations were tested." (PMID 29568401, 2018). "KIT and REST have been implicated as tumor and metastasis suppressors in colorectal cancer." (PMID 30429477, 2018).
tumor (continued). "In their case report, the tumor showed positive staining for KIT, a stem cell marker, and the tumor was considered to be of stem cell origin on the ground that the transitional tumor cells of both histological components showed positive staining for KIT." (PMID 29900476, 2018). "Thus, osteoclasts produce stem cell factor, stimulating PC cells to increase c-KIT expression and, subsequently, their migration from the primary tumour to bones." (PMID 29207991, 2017). "Mutations of KIT and PDGFRA are the most common causes of GIST, which can develop in any part of the gastrointestinal tract with a different prognosis dependent on the tumor location." (PMID 28589146, 2017). "Taken together these results suggest that c-KIT could be involved in the differentiation of thyroid cells and in tumor progression." (PMID 28301608, 2017). "Previously, we identified similar genes and pathways that might drive GIST tumor malignancy by transcriptome analysis of KIT+ cells isolated from 4 metastatic, imatinib-resistant tumors and 8 primary, untreated tumors." (PMID 29371979, 2017). "C-KIT is a protein encoded by the proto-oncogene KIT, mutations of which may play a role in the early stages of tumour development." (PMID 28443572, 2017). "Immunoblots of tumor samples have shown that a minority of GISTs without KIT mutations exhibit high levels of PDGFRA phosphorylation." (PMID 28947997, 2017). "Tumours showing the highest c-KIT RQ had the highest number of Ki67-positive cells." (PMID 29207991, 2017). "This makes crenolanib an attractive agent in the treatment of mutant-KIT tumor entities." (PMID 29137311, 2017). "Inhibition of ABL1 likely reduces the anti-tumor effectiveness of sole KIT inhibition in GIST." (PMID 27965460, 2017). "One noticeable difference in the killing of the afatinib H1975 tumor cells between [siERBB3 + si-c-MET + si-c-KIT] and [dasatinib + afatinib] was the relative impact of blocking autophagosome formation and of blocking eIF2α-dependent endoplasmic reticulum stress signaling." (PMID 26934000, 2016). "Studies comparing 400 with 800 mg IM daily in advanced disease showed no clinical benefit of IM 800 mg daily, except for tumours with KIT exon 9 mutations." (PMID 27999655, 2016). "MiR-193a targets c-KIT and acts as a tumor suppressor in AML." (PMID 26506237, 2016). "Mutational analysis did not reveal any mutation in PDGFRα or KIT, and suggested the possibility of a low-grade tumor other than GIST." (PMID 27842558, 2016). "This revealed two tumour subclones; one with a KIT mutation that responded to imatinib and a second KIT-wild-type subclone that did not respond to imatinib." (PMID 27502704, 2016). "The engrafted GIST tumor contained a 51-nucleotide deletion in exon 11 of KIT (r.1667_1717 del/p." (PMID 25963555, 2015). "The epigenetic profile of the tumour matches that of other KIT-mutant tumours." (PMID 26102504, 2015). "KIT encodes a receptor tyrosine kinase type III and activation mutations are associated with a number of tumor types; however, decreased KIT expression has been identified in malignant thyroid lesions compared to benign lesions which is consistent with our findings." (PMID 25923053, 2015).
tumor (continued). "In our work, we tested the in vitro efficacy of GANT61 (a GLI-inhibitor) and demonstrated that this treatment could affect the viability of GIST cells and modulate the expression of key genes for tumor progression, such KIT and CDKN1A." (PMID 26544626, 2015). "Due to insufficient clinical data the tumours were initially identified as primary tumours with activating KIT exon 11 mutations and no secondary resistance mutations were evaluated." (PMID 25886408, 2015). "The fact that restoration of tumor suppressor activity by PP2A-activating drugs has anti-leukemic effects in both KIT-positive and KIT-negative AML cells suggests that salvaging PP2A function could represent an innovative therapeutic target in AML." (PMID 25015035, 2014). "Finally, xenografted tumors maintain properties comparable to that of patient’s GIST tumor tissue, including cellular histology, KIT expression and FDG-avidity on PET scan." (PMID 24507750, 2014). "In addition, only in regorafenib treated tumours a slight inhibition of KIT and AKT activation was observed." (PMID 25132955, 2014). "Immunostaining showed that the tumor cells were positive for both ALK and KIT expression, and it was thus difficult to distinguish whether the tumor was an IMT or GIST." (PMID 24938355, 2014). "They concluded that the tumour-suppressive role of miR-34a may be potentially relevant to the repressed c-KIT expression in CRC cells." (PMID 25213795, 2014). "Since it is known that KIT may show sequence mutations in MCTs, samples for canine KIT promotorial region sequencing were collected from both healthy dogs (28 blood samples) and from animals affected by MCT (23 archival tumor biopsies)." (PMID 25084283, 2014). "We retrospectively investigated 6 cases of this very rare neoplasm in order to investigate the mutational status of KRAS, EGFR, PDGFR-α and KIT, as well as the immunohistochemical expression pattern of CD117, EGFR and COX-2, and possibly find new therapeutic targets." (PMID 24934485, 2014). "In our study, we also found that combination of AUY922 and rapamycin could more effectively downregulate KIT expression and inhibit tumor growth in IM-resistant GIST cells in vitro and in vivo compared with individual drug alone." (PMID 25375091, 2014). "The spindle cells were positive for both ALK and KIT, and it was thus difficult to determine whether the tumor was an IMT or a GIST." (PMID 24938355, 2014). "Chi-2 analyses were performed to search for a correlation between KIT status and tumor response." (PMID 25174682, 2014). "Two cases showed KIT positivity in less than 30% of the tumor cells." (PMID 23953746, 2013). "Adding imatinib to anti-KIT dTc infusions may augment efficacy through favorable immunomodulation within the tumor microenvironment, allowing the dTc to mediate enhanced tumor cell lysis." (PMID 23433424, 2013). "Furthermore, siRNA knockdown of SCF or blockade of c-KIT can inhibit myeloid-derived suppressor cell expansion, Treg development and tumor angiogenesis, producing a synergistic therapeutic effect in combination with immunotherapy." (PMID 24302925, 2013). "However, in all nodular-type KSs (cases 1, 3, 5, 6, and 14), the tumor cells diffusely expressed c-KIT, and some of the intratumoral vessels were also positive." (PMID 23936513, 2013). "Imatinib is more effective in patients with mutations in KIT exon 11 than in patients with no tumor mutations (wild type) or exon 9 mutations." (PMID 23637977, 2013). "It is likely that ligand-independent KIT activation due to gain-of-function mutations in the KIT gene is the main mechanism of GIST oncogenesis, whereas the ligand-dependent activating mechanism is the crucial reason for tumor proliferation." (PMID 23420128, 2013). "In primary tumors, higher levels of KIT (P=0.016) were observed in patients with tumor size ≤3 cm." (PMID 24649266, 2013). "When co-cultured with KIT+ tumor cells, both 1st and 2nd gen dTc proliferated and produced IFNγ." (PMID 23433424, 2013).